PDE4A (phosphodiesterase 4A)
Description:
Hydrolyzes the second messenger 3',5'-cyclic AMP (cAMP), which is a key regulator of many important physiological processes. [Isoform 1]: Efficiently hydrolyzes cAMP. [Isoform 2]: Efficiently hydrolyzes cAMP. [Isoform 3]: Efficiently hydrolyzes cAMP. The phosphodiesterase activity is not affected by calcium, calmodulin or cyclic GMP (cGMP) levels. Does not hydrolyze cGMP. [Isoform 4]: Efficiently hydrolyzes cAMP. [Isoform 6]: Efficiently hydrolyzes cAMP. [Isoform 7]: Efficiently hydrolyzes cAMP.
Synonyms: DPDE2; PDE4; PDE46
Tractability: Small molecule: an approved drug acts on it; a structure with a bound ligand is known; a high-quality ligand is known; it has a high-quality binding pocket; it belongs to a druggable protein family. Antibody: UniProt places it where antibodies can reach, with high confidence; its Gene Ontology location is reachable by antibodies, with high confidence; the Human Protein Atlas places it where antibodies can reach. PROTAC: it is named in the literature on targeted protein degradation; UniProt records ubiquitination sites on it; ubiquitination databases record sites on it; a small molecule that binds it is known.
Target class: Enzyme; Phosphodiesterase 4A; Phosphodiesterase; Phosphodiesterase 4
Chemical probes: ML-030
Gene: Protein-coding gene on chromosome 19 (10,416,773 to 10,469,630, forward strand). Ensembl gene ENSG00000065989.
Subcellular location: Cytoplasm, perinuclear region (Isoform 1); Cytoplasm, perinuclear region (Isoform 2); Cell projection, ruffle membrane; Cytoplasm, cytosol (Isoform 3); Membrane (Isoform 4); Cytoplasm, perinuclear region (Isoform 6); Cytoplasm, cytosol (Isoform 7); Membrane
Subcellular location (Human Protein Atlas): Plasma membrane
Pathways (Reactome):
Signal Transduction: DARPP-32 events; G alpha (s) signalling events
Gene Ontology:
Molecular function: 3',5'-cyclic-AMP phosphodiesterase activity; cAMP binding; protein binding; 3',5'-cyclic-GMP phosphodiesterase activity; 3',5'-cyclic-nucleotide phosphodiesterase activity; phosphoric diester hydrolase activity
Biological process: G protein-coupled receptor signaling pathway; negative regulation of cAMP/PKA signal transduction; signal transduction; cAMP catabolic process
Cellular component: perinuclear region of cytoplasm; plasma membrane; cytosol; membrane; cytoplasm; ruffle membrane
Genetic constraint (gnomAD): Loss-of-function variants: 21 observed, 69.72 expected, observed/expected ratio (o/e) 0.3, 90% interval 0.21 to 0.43. The upper end of that interval is the gene's LOEUF score, 0.43, which puts it in group 1 of 6, group 1 being the genes least tolerant of losing a copy. Missense variants: 957 observed, 1,191 expected, observed/expected ratio (o/e) 0.8, 90% interval 0.76 to 0.85. Synonymous variants: 463 observed, 497.3 expected, observed/expected ratio (o/e) 0.93, 90% interval 0.86 to 1.
Homologues: Orthologues: chimpanzee PDE4A (99% identical), macaque PDE4A (97% identical), dog PDE4A (87% identical), guinea pig PDE4A (83% identical), mouse Pde4a (81% identical), pig PDE4A (77% identical), rat Pde4a (72% identical), tropical clawed frog pde4a (66% identical), zebrafish pde4a (64% identical), rabbit PDE4A (56% identical), Drosophila melanogaster Pde8 (16% identical), Caenorhabditis elegans pde-3 (15% identical), and 2 more. Paralogues in human: PDE4D (57% identical), PDE4B (57% identical), PDE4C (50% identical), PDE3A (19% identical), PDE3B (18% identical), PDE1C (18% identical), PDE8B (17% identical), PDE8A (17% identical), PDE6A (17% identical), PDE1B (17% identical), PDE6B (16% identical), PDE6C (16% identical), and 8 more.
Diseases named in the same sentence as PDE4A in open-access papers:
PDE4A is named in the same sentence as 268 diseases in open-access papers, as found by Europe PMC text mining. Sharing a sentence is not in itself a finding about the gene and the disease. The quoted sentences say what the papers report.
asthma (85 papers, 2010 to 2026). "Interestingly, PDE4A, encoding one phosphodiesterases targeted by asthma medication, was down-regulated in the ileum of patients with asthma." (PMID 34332619, 2021).
psoriatic arthritis (39 papers, 2015 to 2026). Joint inflammation associated with psoriasis. "Similarly, a PDE4A inhibitor, apremilast, was already on the market for psoriatic arthritis in 2014 and is currently being explored as a treatment for RA, with initial success in a mouse model." (PMID 33106501, 2020).
depression (36 papers, 2008 to 2026). "The study identified five genetic markers for increased risk of depression in women, three of which were rs201432982 for PDE4A, rs62640397, and rs79442975 for FDX1L, and the remaining two were rs820182 and rs820148 for MYO15B." (PMID 37140907, 2023). "It has been reported that changes in PDE4B concentration are associated with depression and anxiety-like behaviors, while PDE4A may play a neuroprotective role by modulating neuroinflammation." (PMID 36979232, 2023). "Furthermore, we identified that loss of PDE4A can prevent both dietary and genetically induced depression-like behavior phenotype in mice." (PMID 31076569, 2019). "According to a review on CNS and PDEs, it is pointed out that PDE4A, 4B and 4D may participate in depression." (PMID 36142518, 2022). "Deficiency of phosphodiesterase 4A (PDE4A), an enzyme that degrades cAMP and modulates stimulatory regulative G protein (Gs)-coupled G protein-coupled receptor signaling, protected animals either from genetic- or dietary-induced depression phenotype." (PMID 31076569, 2019). "Variants of PDE4A may reduce neuronal firing and dysregulate negative feedback through the hypothalamic‒pituitary‒adrenal axis, leading to the development of depressive disorders." (PMID 37140907, 2023). "When compared to wild-type (WT) mice, PDE4A KO or PDE4B KO mice proved anxiety characteristics along with higher corticosterone levels, while PDE4B KO mice also showed increased long-term depression." (PMID 41602587, 2026). "Thus, this gene may be involved in synaptic plasticity affected by antidepressants, and variants in PDE4A might decrease neuronal firing and dysregulate negative feedback via the hypothalamus-pituitary-adrenal axis, which predisposes individuals to depressive disorder." (PMID 32555505, 2020). "The amygdala is involved in depression with many neuronal circuits within the hypothalamus; however, this brain region showed no statistical difference in PDE4 activity levels between the ND and HFD in either WT or PDE4A−/− mice." (PMID 31076569, 2019). "Although some studies have shown that exercise can improve the inflammatory response and reduce the depression-like behavior of aging rats; however, MIIT did not significantly alter PDE4A/PDE4B expression in this study, so it may not have been through the PDE4A/PDE4B pathway." (PMID 36979232, 2023).
COVID-19 (19 papers, 2021 to 2025). A disease caused by infection with severe acute respiratory syndrome coronavirus 2. "In contrast to the negative correlations seen in the lungs and blood, we show that a genetic tendency for higher expression of PDE4A in monocytes is associated with critical COVID-19." (PMID 37198478, 2023). "The severe COVID-19 risk alleles are associated with decreased expression of PDE4A, while they are protective for SLE." (PMID 36327221, 2022). "At the genetic level, COVID-19 hospitalization and MS share five risk genes within two loci, including TNFAIP8, HSD17B4, CDC37, PDE4A, and KEAP1, which may mediate the association between MS and COVID-19." (PMID 37395896, 2023).
Anxiety (16 papers, 2015 to 2026). Intense feelings of nervousness, tension, or panic often arise in response to interpersonal stresses. "Measurement of motor anxiety (open field test) revealed no major differences between WT and PDE4A−/− fed either ND or HFD or between the ob/ob and PDE4A−/−:ob/ob mice." (PMID 31076569, 2019).
schizophrenia (15 papers, 2013 to 2025). A major psychotic disorder characterized by abnormalities in the perception or expression of reality. "Furthermore, a PDE4A SNP was associated with schizophrenia in a Japanese population." (PMID 38790238, 2024). "Besides the downregulation of PDE4B in brain samples, PDE4A was downregulated in blood samples from schizophrenia patients." (PMID 38790238, 2024). "Interestingly, PDE4B was found to be upregulated in blood samples of patients with schizophrenia (p-value = 0.0011), while PDE4A was found to be downregulated (p-value = 0.0052)." (PMID 38790238, 2024). "Additionally, the analysis of blood samples from affected individuals reveals downregulation of PDE4A and upregulation of PDE4B, suggesting their potential as biomarkers for schizophrenia." (PMID 38790238, 2024). "Besides, PDE4A was related to heat shock protein B6 (HSPB6), aldehyde dehydrogenase 7A1 (ALDH7A1), A-kinase anchoring protein 1 (AKAP1), adrenoceptor beta 2 (ADRB2), SAG (an arrestin family member which desensitizes GPCR) and DISC1 (disrupted in Schizophrenia 1)." (PMID 38514754, 2024). "We next explored whether PDE4A, PDE4B, PDE4C, and PDE4D are differentially expressed not only in the brain samples but also in blood samples of patients with schizophrenia and thus might serve as biomarkers." (PMID 38790238, 2024).
Obesity (13 papers, 2015 to 2025). Accumulation of substantial excess body fat. "Given the potential central role of PDE4A, we assessed whether mice lacking PDE4A (PDE4A−/−) were protected from the depression-like behavior induced by obesity." (PMID 31076569, 2019).
lung carcinoma (12 papers, 2016 to 2025). "Moreover, hypoxia-inducible factor (HIF) has been linked to PDE4A expression in a subset of lung cancer cell lines during hypoxia, and PDE4A knockdown has been shown to reduce the secretion of vascular endothelial growth factor (VEGF) and has anti-tumor effects in lung cancer xenografts." (PMID 37251402, 2023). "In particular, PDE4A expression is upregulated in various lung cancer cell lines, and its expression can induce epithelial–mesenchymal transition in type 1 alveolar epithelial cells after stimulation with transforming growth factor-β2 (TGF-β2)." (PMID 37251402, 2023). "There are some existing studies on PDE4A in MS and lung cancer." (PMID 37251402, 2023). "Thus, it is clear that PDE4A is a promising therapeutic target in MS and lung cancer and warrants further investigation." (PMID 37251402, 2023). "PDE4A and PDE4D promote HIF signaling in lung cancer through cAMP-PKA/EPAC pathways." (PMID 38233872, 2024).
cardiac hypertrophy (11 papers, 2010 to 2025). "Interestingly, in a rat model of cardiac hypertrophy induced by thoracic aortic banding, the total cAMP hydrolytic activity and activities of PDE4 and PDE3 isoforms—including PDE4A and PDE4B—are reduced, whereas PDE4D activity remains unchanged." (PMID 40136709, 2025). "Furthermore, during cardiac hypertrophy in rats, there is a decrease in PDE4A, and PDE4B proteins and mRNA expressions, that accompany β-adrenergic desensitization, indicating some failures of PDE4s in cardiac pathologies." (PMID 36142518, 2022).
colon cancer (10 papers, 2012 to 2025). "PDE4 consists of four subtypes, PDE4A, PDE4B, PDE4C and PDE4D, and is involved in several human malignancies including prostate cancer, leukemia, colon cancer and glioma." (PMID 34066000, 2021).
heart failure (10 papers, 2017 to 2025). Inability of the heart to pump blood at an adequate rate to meet tissue metabolic requirements. "This review highlights the cardiac PDE4 isoforms PDE4A, PDE4B and PDE4D, focusing on their distinct localisation and contributions to cardiac physiology and pathophysiology, particularly in heart failure and arrhythmias." (PMID 40136709, 2025).
allergic asthma (8 papers, 2008 to 2023). A asthma with a basis in a pathological type I hypersensitivity reaction. "Preclinical evidence of PDE4 targeting in a rat model of allergic asthma indicated that ovalbumin sensitization and challenge significantly increased the activity of PDE4 and mRNA expression of different PDE4 isoforms, including PDE4A, PDE4C and PDE4D." (PMID 37765223, 2023). "BA was found to selectively inhibit the enzymatic activity of PDE4A and 4B to relieve allergic asthma." (PMID 37007037, 2023).
Behçet’s disease (8 papers, 2020 to 2025). "Inhibitors of phosphodiesterase 4A have been investigated as potential therapeutic agents for the treatment of autoimmune uveitis and Behçet disease, one of the uveitis-associated systemic diseases." (PMID 40270958, 2025).
melanoma (8 papers, 2012 to 2026). A malignant, usually aggressive tumor composed of atypical, neoplastic melanocytes. "Silencing PDE4B or PDE4D significantly reduced PDE4 activity in melanoma cells, whereas PDE4A had no such effect, suggesting that PDE4B and PDE4D play crucial roles in regulating PDE4 activity in melanoma." (PMID 40129976, 2025).
Arrhythmia (7 papers, 2010 to 2025). Any cardiac rhythm other than the normal sinus rhythm. "Numerous studies indicate that inhibition of PDE3A/B can lead to arrhythmia and increased mortality; PDE4 plays an important role as a regulator of central nervous system function while inhibition of PDE4A can increase heart and respiratory rates." (PMID 33668128, 2021).
glioma (7 papers, 2016 to 2025). A benign or malignant brain and spinal cord tumor that arises from glial cells (astrocytes, oligodendrocytes, ependymal cells). "Relative expression of PDE4A protein in core-derived TICs was 2.5 fold more than periphery-derived cells of glioma." (PMID 29158883, 2017). "For instance, PDE4A expression is elevated in central nervous system tumor cells, and PDE4B expression in increased in hematologic malignancies, whereas hypermethylation of PDE4C promoter sites was reported in high-grade glioma samples." (PMID 34066000, 2021).
breast carcinoma (6 papers, 2016 to 2026). "Conversely, although PDE4A expression is also elevated in estrogen receptor-positive and progesterone receptor-positive breast cancer patients, patients with high PDE4A expression have longer progression-free survival (PFS) and overall survival (OS)." (PMID 40129976, 2025). "Inhibition of PDE4A in breast cancer stem cells increases cAMP levels and PKA activity, which upregulates PTEN and induces cell cycle arrest." (PMID 38233872, 2024). "Surprisingly, further analysis of established breast cancer cell lines using datasets from Cancer Cell Line Encyclopedia showed that PDE4A, rather than PDE4B was overexpressed in TNBC cell lines compared with ER+ ones." (PMID 27901486, 2016).
glioblastoma (6 papers, 2016 to 2025). The most malignant astrocytic tumor (WHO grade IV). "PDE4A has been found to be expressed in medulloblastomas, glioblastomas, oligodendrogliomas, ependymomas, and meningiomas, and may be a new target for treating brain tumors." (PMID 40129976, 2025). "Furthermore, the expression of several PDEs is upregulated in glioblastoma cells, and the specific isoforms PDE1C, PDE4A, PDE4B, PDE4D and PDE5 have been suggested as therapeutic targets in glioblastoma." (PMID 34575827, 2021).
prostate carcinoma (6 papers, 2015 to 2024). A carcinoma that arises from epithelial cells of the prostate gland. "Regarding prostate cancer, PDE4A is downregulated, PDE4D increased overall, but PDE4D7 is upregulated when androgen-sensitive and downregulated if not." (PMID 35163131, 2022).
Hypertension (5 papers, 2022 to 2024). The presence of chronic increased pressure in the systemic arterial system. "To initially investigate PDE4 expression after hypertension, we evaluated mRNA levels of each PDE4 isoform (Pde4a-d) in control and hypertensive mice aortas." (PMID 35058564, 2022).
brain tumor (4 papers, 2013 to 2023). "An examination of 37 human pediatric and adult brain tumor specimens including astrocytomas, medulloblastomas, oligodendrogliomas, ependymomas, and meningiomas all exhibited high levels of PDE4A expression, primarily in tumor cells." (PMID 26283963, 2015). "Furthermore, overexpression of a super-short, brain specific isoform of PDE4A, PDE4A1, accelerated brain tumor growth in mice bearing intracranial xenografts of human glioma cells." (PMID 26283963, 2015).
hepatocellular carcinoma (4 papers, 2024 to 2025). A malignant tumor that arises from hepatocytes. "It is reported that most patients with hepatocellular carcinoma (HCC) show elevated PDE4A expression in tumor tissues relative to corresponding adjacent liver tissues." (PMID 40129976, 2025).
leukemia (4 papers, 2014 to 2021). A malignant (clonal) hematologic disorder, involving hematopoietic stem cells and characterized by the presence of primitive or atypical myeloid or lymphoid cells in the bone marrow and the blood. "PDE4A, encodes one of phosphodiesterases (PDEs), is abundantly expressed in leukemia cell lines." (PMID 31523525, 2019). "Therefore, the PDE4A on the K-562 cell line seems to be the specific and maybe a potential target to tumor therapies in this type of leukemia." (PMID 26136685, 2015).
lung adenocarcinoma (4 papers, 2015 to 2024). A carcinoma that arises from the lung and is characterized by the presence of malignant glandular epithelial cells. "In an exploratory analysis, the protein and mRNA expression levels of DGKa, PDE4A and PDE4D were examined in the five EGFR-mutant lung adenocarcinoma cell lines in an effort to explore whether DGKa regulates MTOR transcription through modulation of cAMP levels." (PMID 26639561, 2015).
ovarian carcinoma (4 papers, 2017 to 2024). A malignant neoplasm originating from the surface ovarian epithelium. "In 2010, another investigation showed that this isoflavonoid as a tyrosine kinase inhibitor activates autophagy in ovarian cancer cells through the PDE4A/PDE4A4 (phosphodiesterase 4A) and SQSTM1 pathways." (PMID 36497321, 2022).
Huntington disease (3 papers, 2011 to 2021). Huntington disease (HD) is a rare neurodegenerative disorder of the central nervous system characterized by unwanted choreatic movements, behavioral and psychiatric disturbances and dementia. "Strikingly, the cognitive deficits seen in a mouse model of Huntington's disease (R6/1) can be rescued by the antipsychotic drug fluoxetine, a potent inhibitor of phosphodiesterase type IV (PDE4A, B, C and D)." (PMID 21298101, 2011).
systemic sclerosis (3 papers, 2017 to 2024). A chronic disorder, possibly autoimmune, marked by excessive production of collagen which results in hardening and thickening of body tissues. "Specifically, rs892085 and rs322151, located downstream of PDE4A, have been associated with Ps and PsA and systemic sclerosis, respectively." (PMID 38540428, 2024).
gastric cancer (2 papers, 2021 to 2024). A primary or metastatic malignant neoplasm involving the stomach. "Finally, we carried out qRT-PCR analysis of the expression levels of RGS2, GNAI2, ANXA5, MARCKS, CD36, NRP1, and PDE4A in gastric cancer cells." (PMID 38274323, 2024).
idiopathic dilated cardiomyopathy (2 papers, 2022 to 2025). Decreased function of the heart associated with cardiac enlargement and congestive heart failure, of unknown cause. "Studies show that PDE4A and PDE4D are significantly reduced in the hearts of patients with idiopathic dilated cardiomyopathy." (PMID 39662482, 2025).
oral cancer (2 papers, 2019 to 2021). "Glycolytic enzymes Aldoa, Hk2, Tpi1, Pgam2, Pfkl, and Pkm2 as well as the PKA-AMPK pathway genes Prkaa2, Pde4a, Pde10a, Ywhag, and Crebbp were downregulated by BRBs during oral cancer chemoprevention." (PMID 31336728, 2019). "Therefore, PDE4A might be an important target gene involved in oral submucosal fibrosis and oral cancer." (PMID 34819854, 2021).